PSMD10 (proteasome 26S subunit, non-ATPase 10)
Description:
Acts as a chaperone during the assembly of the 26S proteasome, specifically of the PA700/19S regulatory complex (RC). In the initial step of the base subcomplex assembly is part of an intermediate PSMD10:PSMC4:PSMC5:PAAF1 module which probably assembles with a PSMD5:PSMC2:PSMC1:PSMD2 module. Independently of the proteasome, regulates EGF-induced AKT activation through inhibition of the RHOA/ROCK/PTEN pathway, leading to prolonged AKT activation. Plays an important role in RAS-induced tumorigenesis. Overexpression is leading to phosphorylation of RB1 and proteasomal degradation of RB1. Regulates CDK4-mediated phosphorylation of RB1 by competing with CDKN2A for binding with CDK4. Involved in regulation of NF-kappa-B by retaining it in the cytoplasm. Binds to the NF-kappa-B component RELA and accelerates its XPO1/CRM1-mediated nuclear export.
Synonyms: p28; dJ889N15.2; p28(GANK)
Tractability: Small molecule: a structure with a bound ligand is known. PROTAC: ubiquitination databases record sites on it; its protein half-life has been measured; a small molecule that binds it is known.
Gene: Protein-coding gene on chromosome X (108,084,202 to 108,091,619, reverse strand). Ensembl gene ENSG00000101843.
Subcellular location: Cytoplasm; Nucleus
Subcellular location (Human Protein Atlas): Cytosol; Mid piece; Calyx; Perinuclear theca; Primary cilium tip; Principal piece
Pathways (Reactome):
Metabolism of proteins: Proteasome assembly
Gene Ontology:
Molecular function: protein binding; RNA polymerase II-specific DNA-binding transcription factor binding
Biological process: negative regulation of apoptotic process; negative regulation of MAPK cascade; negative regulation of release of cytochrome c from mitochondria; negative regulation of transcription by RNA polymerase II; positive regulation of cell growth; positive regulation of cyclin-dependent protein serine/threonine kinase activity; positive regulation of proteasomal ubiquitin-dependent protein catabolic process; positive regulation of protein ubiquitination; proteasome regulatory particle assembly; regulation of transcription by RNA polymerase II
Cellular component: cytoplasm; cytosol; nucleus; proteasome complex; proteasome regulatory particle, base subcomplex
Homologues: Orthologues: chimpanzee PSMD10 (100% identical), macaque PSMD10 (99% identical), pig PSMD10 (99% identical), dog PSMD10 (99% identical), rabbit PSMD10 (99% identical), rat Psmd10 (95% identical), mouse Psmd10 (94% identical), tropical clawed frog psmd10 (78% identical), zebrafish psmd10 (72% identical). Paralogues in human: DTHD1 (23% identical).
Diseases named in the same sentence as PSMD10 in open-access papers:
PSMD10 is named in the same sentence as 47 diseases in open-access papers, as found by Europe PMC text mining. Sharing a sentence is not in itself a finding about the gene and the disease. The quoted sentences say what the papers report.
breast carcinoma (11 papers, 2015 to 2024). "Therefore, PSMD10 is overexpressed in numerous types of cancers, including hepatocellular carcinoma, breast cancer and pancreatic cancer." (PMID 35095928, 2021). "High expression of PSMD9 was associated with post-radiotherapy recurrence in cervical and breast cancer, and endogenous PSMD10 interacted with GRP78 to regulate endoplasmic reticulum stress, which might provide a therapeutic target for homocysteine-induced liver injury." (PMID 37349676, 2023). "Additionally, other PSM genes have been associated with cancer progression (e.g. PSMD9 (p27) and PSMD10 (p28)), increased radiation sensitivity in breast cancer (e.g. absence of p27), as well as, increased risk of colorectal cancer (e.g. PSMB8 and PSMB9)." (PMID 36123629, 2022). "PSMD10, on the other hand, plays a role in EMT and cell migration, further promoting cancer cell invasion and metastasis, especially in breast cancer." (PMID 39469643, 2024). "The levels of PSMD1, PSMD2, PSMD3, PSMD7, PSMD10, PSMD12, and PSMD14 are high in breast cancer tissue compared to normal tissues." (PMID 36934426, 2023). "The study revealed a significant upregulation in AP1M2, PSMD10, and RPL2 expression in breast cancer tissue compared to normal tissues." (PMID 38418940, 2024).
hepatocellular carcinoma (11 papers, 2012 to 2025). A malignant tumor that arises from hepatocytes. "Studies have shown that PSMD10 is associated with tumor diseases, such as hepatocellular carcinoma and thyroid cancer." (PMID 35574315, 2022). "Consistent over-expression of PSMD10 promotes tumor growth and inhibits apoptosis in hepatocellular carcinomas cells by enhancing the UPR and up-regulating GRP78 expression." (PMID 34666830, 2021). "Gankyrin, also known as PSMD10, serves as an oncogene in various malignant cancers, including hepatocellular carcinoma, colorectal cancer, gastric cancer, prostate cancer, ovarian cancer, and cholangiocarcinoma." (PMID 32051393, 2020). "Hepatocellular cancer patients with higher expression of PSMD10 were found to be characterized by increased tumor size, vascular invasion as well as intrahepatic or distant metastasis and would suffer a poor OS or shorter DFS than low-expression patients." (PMID 27966459, 2017). "Gankyrin (also known as PSMD10, p28 and Nas6p) is an oncoprotein overexpressed in many malignancies including hepatocellular carcinoma, cholangiocellular carcinoma, colorectal cancer and lung cancer." (PMID 28160571, 2017). "In addition to normal biological functions, emerging evidences support that PSMD10 functions as an oncogene in many cancers including hepatocellular carcinomas, gliomas lung cancer, and colon, and so on." (PMID 34666830, 2021). "However, what contradicts with us is that PSMD10 protects hepatocellular carcinoma cells from ER stress-induced apoptosis through the enhancement of UPR signaling." (PMID 34666830, 2021). "The 26S proteasome non-ATPase regulatory subunit 10 PSMD10/gankyrin (O75832) is an oncoprotein overexpressed in most hepatocellular carcinomas." (PMID 41463016, 2025). "PSMD10 (Proteasome 26S Subunit, Non-ATPase 10), also known as Gankyrin, was initially cloned from a cDNA library obtained from a hepatocellular carcinoma." (PMID 35409173, 2022). "P28GANK, also named as PSMD10 and gankyrin, is a highly conserved protein with six ankyrin repeats in mammals, which is located on human chromosome Xq22.3 and cloned by complementary DNA subtractive hybridization in hepatocellular carcinoma (HCC)." (PMID 22913315, 2012).
colorectal cancer (6 papers, 2012 to 2025). A primary or metastatic malignant neoplasm that affects the colon or rectum. "According to a previous study, hsa-miR-1248 has been suggested to function as a tumor-suppressive miRNA in colorectal cancer by targeting and inhibiting PSMD10, indicating a potential regulatory role in colorectal tumorigenesis." (PMID 41465474, 2025). "Studies have indicated important roles played by PSMD10 in the pathogenesis of liver cancers and colorectal cancers, and PSMD 10 involved in regulating the proliferation and metastasis of thyroid cancers." (PMID 33557781, 2021). "Expression of PSMD10 was shown in endometrial, breast, and colorectal cancer and very recently in human CCA." (PMID 26313366, 2015).
glioma (5 papers, 2012 to 2023). A benign or malignant brain and spinal cord tumor that arises from glial cells (astrocytes, oligodendrocytes, ependymal cells). "Statistically, the mRNA expression of PSMD1/4/5/8/9/11/12 tended to increase as glioma grade increased, whereas the mRNA expression of PSMD10 tended to decrease with increasing glioma grade." (PMID 37485655, 2023).
myeloma (5 papers, 2021 to 2024). "Another study showed that ectopic expression of miR-214 inhibits myeloma cell growth and induces apoptosis by inhibiting PSMD10." (PMID 34666830, 2021). "In multiple myeloma, LINC00665 upregulates PSMD10 and ASF1B by sponging miR-214-3p, thereby promoting proliferation and inhibition of apoptosis of multiple myeloma cells." (PMID 35563845, 2022).
thyroid cancer (3 papers, 2021 to 2025). "PSMD10 contributes to tumorigenesis through proteasomal regulation and has been implicated in liver and thyroid cancers." (PMID 40963856, 2025).
gastric cancer (2 papers, 2012 to 2023). A primary or metastatic malignant neoplasm involving the stomach. "Therefore, the upregulation of PSMD10 gene reported in EBV-associated gastric cancer maybe associated with the expression of EBNA1 in cancerous cells infected with EBV." (PMID 36624687, 2023).
Insulin resistance (2 papers, 2022 to 2025). Increased resistance towards insulin, that is, diminished effectiveness of insulin in reducing blood glucose levels. "These genes have been involved in insulin resistance and secretion (ATM, PTPRN2, PSMD10, and NSF), adipogenesis (SLC25A24 and PAX8), inflammatory processes (TNFRSF8 and SLIT3), and mitochondrial processes (PM20D1 and LCLAT1)." (PMID 36535927, 2022).
intrahepatic cholangiocarcinoma (2 papers, 2015 to 2021). A carcinoma that arises from the intrahepatic bile duct epithelium in any site of the intrahepatic biliary tree. "Recent report provided evidence that miR-605 significantly represses intrahepatic cholangiocarcinoma (ICC) cell proliferation and invasion by down-regulating PSMD10 through binding to the 3′UTR of PSMD10." (PMID 34666830, 2021).
oral cancer (2 papers, 2022 to 2025). "In oral cancer, overexpressed PSMD10/Gankyrin was detected in cancer tissues and premalignant oral lesions." (PMID 35409173, 2022). "Furthermore, PSMD10 is regarded as a biomarker for epithelial carcinogenesis, and overexpression has been observed in human oral cancer." (PMID 41235252, 2025).
Burkitt lymphoma (1 paper, 2025). A rare form of malignant mature B-cell non-Hodgkin lymphoma. "Additionally, in a separate study, Hashemi and colleagues reported significant PSMD10 overexpression in Burkitt lymphoma (BL)." (PMID 40771905, 2025).
developmental delay (1 paper, 2021). "While there are no conclusive data about degradation of synaptic proteins due to CNVs affecting PSMD10, we hypothesize that deregulation of PSMD10 expression through loss of the genetic material in the locus could contribute to severe MR and developmental delay in our proband and maternal uncle." (PMID 34777475, 2021).
esophageal cancer (1 paper, 2021). A primary or metastatic malignant neoplasm involving the esophagus. "Interestingly, other proteasome subunits were also expressed highly in EC and the elevated expression of PSMA2, PSMA5, PSMC6, PSMD5, PSMD10 indicated poor prognosis of EC patients respectively, which revealed a crucial role of 26S proteasome in esophageal cancer." (PMID 33897885, 2021).
malignant glial tumors (1 paper, 2017). "Among these genes, DMRTA2 encodes a transcription factor involved in human female germ cell development;21KCNG2 encodes a potassium channel subunit whose altered expression has been associated with malignant glial tumors;22 and PSMD10 encodes a regulatory subunit of the 26S proteasome." (PMID 27775072, 2017).
metastasis (1 paper, 2022). The spread or migration of cancer cells from one part of the body (where they first appeared) to another. "In our recent research, PSMD10 was shown to be a promising biomarker of occult liver metastasis in CRC patients." (PMID 36028821, 2022).
pancreatic ductal adenocarcinoma (1 paper, 2015). An infiltrating adenocarcinoma that arises from the epithelial cells of the pancreas. "For PSMD10 there is evidence that positive expression levels associate with short survival time of patients in pancreatic ductal adenocarcinoma tissues." (PMID 25734857, 2015).
Peri-Implantitis (1 paper, 2019). An inflammatory process with loss of supporting bone in the tissues surrounding functioning DENTAL IMPLANTS. "Three common leader genes; PSMD10, SOS1, and WASF3, were identified from the gene clusters linked to peri-implantitis and T2DM each." (PMID 31275749, 2019). "Three leader genes (PSMD10, SOS1, WASF3), eight cross-talk genes (PSMD10, PSMD6, EIF2S1, GSTP1, DNAJC3, SEC61A1, MAPT, and NME1), and one signaling pathway (IL-17 signaling) emerged as peri-implantitis and T2DM linkage mechanisms." (PMID 31275749, 2019).
sarcoma (1 paper, 2024). A usually aggressive malignant neoplasm of the soft tissue or bone. "In cellular experiments, we observed significantly upregulated mRNA expression of CALR, CASP3, BCL10, PSMD7, and PSMD10 in sarcoma cell lines compared to their corresponding normal cell lines." (PMID 39469643, 2024).
tumor (21 papers, 2012 to 2025). "Our results suggest that MNAT1, EIF3F, and PSMD10 are all highly expressed in the low differentiation state, indicating these key genes are critical factors promoting tumor malignancy." (PMID 41235252, 2025). "In recent studies, dysregulation of PSMD10 promotes tumor progression and significantly affects tumor cell proliferation and migration." (PMID 39469643, 2024). "We found that PSMD10 expressed a high copy number in CRC tumor tissues compared with the adjacent normal tissue, and the copy number was further elevated in M_High tissue compared with M_Low tissue, which showed an inverse correlation with miR-1248." (PMID 36028821, 2022). "The tumor suppressor effect of has-miR-1248 in CRC cells was attenuated or enhanced by up-regulating or down-regulating PSMD10, respectively." (PMID 36028821, 2022). "Depletion of several ubiquitinases and proteasome components (DTX3L, UBE2E1, RNF31, RNF115, USP2, USP42, PSMC3, and PSMD10) were also found to inhibit tumor cell migration." (PMID 31278301, 2019). "miR-3619-5p inhibited tumor growth in vivo by inducing the phosphorylation of activator of transcription 3 (STAT3) and retinoblastoma protein (Rb1), thereby targeting PSMD10 to inhibit cell proliferation and induce G1 arrest." (PMID 37349676, 2023). "In the present study, the relative expression of mRNA by real-time PCR showed that PSMD10 and CDK4 genes were over-expressed (P = 0.034; P = 0.006) in the tumor tissues of the Cs+NDMA group hamster’s liver." (PMID 26313366, 2015).
cancer (18 papers, 2012 to 2025). A tumor composed of atypical neoplastic, often pleomorphic cells that invade other tissues. "In addition, overexpression of PSMD10 has been implicated in the development of many cancer types." (PMID 34777475, 2021). "shRNA targeting PSMD10 significantly reduces the viability of cancer cells. miR-214 and miR-137 inhibit proliferation by suppressing PSMD10." (PMID 40806497, 2025). "miRNAs regulate key signaling pathways and target genes (e.g., SNAI1, PSMD10) to exert dual roles (cancer-promoting or cancer-suppressing) in thyroid cancer development." (PMID 40530008, 2025). "For example, PSMD10 is a crucial oncoprotein that is up-regulated in a variety of cancers and has potential in the initiation and progression of tumors." (PMID 33557781, 2021). "PSMD10 overexpression was supposed to substantially contribute to the onset of tumors as observed in various cancer types." (PMID 34839279, 2021). "PSMD10 was earlier shown to be a potential target for cancer therapy." (PMID 36028821, 2022). "Moreover, in various cancers, gankyrin or PSMD-10, a recently discovered small oncogenic protein of 25 kDa, is known to be overexpressed." (PMID 34585958, 2021). "PSMD10 has been demonstrated to promote the proliferation, invasion, metastasis and angiogenesis of cancer cells through PI3K/Akt/HIF-1α signaling, which may depend on promoting the degradation of HIF-1α." (PMID 35095928, 2021).
infection (4 papers, 2019 to 2025). The state of being infected such as from the introduction of a foreign agent such as serum, vaccine, antigenic substance or organism. "Our study found a set of proteasome-encoding genes that included PSMA1, PSMD10, PSMD14 and PSMA4, that were all down-regulated during the early phase of infection." (PMID 30789917, 2019). "In the absence of probiotics, infection by V. coralliilyticus caused an increase in expression of the 26S proteasome non-ATPase regulatory subunit 10 protein (PSMD10) and serine/threonine-protein kinase RIO3 (RIOK3), both of which have been found to inhibit NF-kB activation." (PMID 38650950, 2024).
PSMD10 also shares sentences with these, for which no sentence is quoted: lung carcinoma (4 papers); viral infection (4); multiple myeloma (3); pancreatic cancer (3); cervical cancer (2); liver cancer (2); ovarian carcinoma (2); papillary thyroid carcinoma (2); allergic reaction (1); bladder cancer (1); Cachexia (1); cardiac diseases (1); cholangiocarcinoma (1); colitis (1); COVID-19 (1); diabetes (1); esophageal squamous cell carcinoma (1); glaucoma (1); head and neck cancer (1); infectious disease (1); kidney renal cancer (1); lung adenocarcinoma (1); melanoma (1); non-small cell lung carcinoma (1); osteosarcoma (1); testicular germ cell tumor (1).